TCF24 (transcription factor 24)
Description:
Putative transcription factor.
Synonyms: TCF-24; bHLHa25
Tractability: No criterion of Open Targets' tractability assessment is met for any kind of drug.
Gene: Protein-coding gene on chromosome 8 (66,946,491 to 66,962,591, reverse strand). Ensembl gene ENSG00000261787.
Subcellular location: Nucleus
Gene Ontology:
Molecular function: protein binding; DNA-binding transcription factor activity, RNA polymerase II-specific; RNA polymerase II transcription regulatory region sequence-specific DNA binding; protein dimerization activity
Biological process: developmental process; regulation of transcription by RNA polymerase II
Cellular component: nucleus
Genetic constraint (gnomAD): Loss-of-function variants: 3 observed, 5.25 expected, observed/expected ratio (o/e) 0.57, 90% interval 0.26 to 1.44. That is too few expected variants to judge how well the gene tolerates losing a copy. Missense variants: 210 observed, 169.2 expected, observed/expected ratio (o/e) 1.24, 90% interval 1.11 to 1.39. Synonymous variants: 108 observed, 80.11 expected, observed/expected ratio (o/e) 1.35, 90% interval 1.15 to 1.58.
Homologues: Orthologues: chimpanzee TCF24 (99% identical), macaque TCF24 (93% identical), pig TCF24 (91% identical), rabbit TCF24 (88% identical), dog TCF24 (86% identical), guinea pig TCF24 (84% identical), mouse Tcf24 (83% identical), rat Tcf24 (83% identical), tropical clawed frog tcf24 (62% identical), zebrafish TCF24 (58% identical), Drosophila melanogaster HLH54F (23% identical), Drosophila melanogaster twi (23% identical), and 3 more. Paralogues in human: TCF23 (46% identical), TCF21 (32% identical), MSC (31% identical), PTF1A (27% identical), TCF15 (26% identical), HAND2 (25% identical), HAND1 (23% identical), SCX (23% identical), FIGLA (23% identical), TWIST2 (22% identical), BHLHA9 (21% identical), TWIST1 (21% identical), and 1 more.
Diseases named in the same sentence as TCF24 in open-access papers:
TCF24 is named in the same sentence as 2 diseases in open-access papers, as found by Europe PMC text mining. Sharing a sentence is not in itself a finding about the gene and the disease. The quoted sentences say what the papers report.
Alzheimer disease (1 paper, 2019). A progressive, neurodegenerative disease characterized by loss of function and death of nerve cells in several areas of the brain leading to loss of cognitive function such as memory and language. "TCF24, rs182838111 located at chromosome 8, increased the risk of Alzheimer’s disease via family meta-analyses." (PMID 30823506, 2019).
cancer (1 paper, 2020). A tumor composed of atypical neoplastic, often pleomorphic cells that invade other tissues. "The top activated transcriptional regulators were CENPA, FOXM1, TCF24, and MYBL2, which were linked to 875, 845, 843, and 840 cancer-specific enhancer probes, respectively." (PMID 32925947, 2020).